BCL2 (BCL2 apoptosis regulator)
Diseases named in the same sentence as BCL2 in open-access papers (continued):
Sharing a sentence is not in itself a finding about the gene and the disease.
breast carcinoma (continued). "We also found that the black garlic extract, in combination with venetoclax, a BCL-2 inhibitor, synergistically kills the estrogen receptor-positive breast cancer cells." (PMID 37352173, 2023). "Suppression of BCL2 can upregulate the expression of beclin‐1, thus leading to apoptosis in breast cancer cells." (PMID 37484971, 2023). "Here, we evaluated the level of serum/glucocorticoid-regulated kinase 1 (SGK1) and B-cell lymphoma 2 (Bcl-2) levels in the corresponding primary breast cancer tissue." (PMID 37370761, 2023). "A calcium phosphate-PEG-polyanion polymer promoted the siRNA delivery targeting anti-apoptotic gene BCL-xL and BCL-2 in breast cancer cell line MCF-7." (PMID 36678782, 2023). "The compound has been reported to trigger apoptosis via the mitochondrial apoptotic pathway in various cancer types, such as breast cancer, gastric carcinoma, and hepatic cancer, by optimizing the Bcl-2/Bax ratio to activate the caspase cascade." (PMID 37759583, 2023). "Our findings are consistent with reports by other authors, who demonstrated increased Bax expression accompanied by endogenous Bcl-2 degradation in iodine-treated human breast cancer cells." (PMID 37373017, 2023). "HULC depletion leads to a decrease in Bcl-2 and an increase in the Bax/Bcl-2 expression ratio in breast cancer cell lines." (PMID 37910386, 2023). "Alg-EO and Alg-Beta induced apoptosis in melanoma and breast cancer cells confirmed by increased Bax/Bcl-2 ratio." (PMID 38017466, 2023). "Bazedoxifene is now being repositioned as a new strategy for treating multiple cancer types (such as breast cancer, pancreatic cancer, colon cancer, etc.)by downregulating anti-apoptotic proteins such as BCL-2." (PMID 37193964, 2023). "This strategy reduces the resistance of colon and breast cancer cells to chemotherapeutic drugs by delivering Bcl-2 siRNA and DOX simultaneously." (PMID 37511335, 2023). "Genistein induced apoptosis in MCF-7 breast cancer cells via regulating ERα expression and altering the bax/bcl-2 ratio." (PMID 36675194, 2023). "NRP1, a transmembrane glycoprotein, contributes to stemness and radioresistance of breast cancer through WTAP-mediated m6A methylation of Bcl-2 mRNA." (PMID 37598390, 2023). "Dab1 promoted cell apoptosis by regulating NF‐κB/Bcl‐2/caspase‐9 pathway, considered as a potential tumor suppressor gene of breast cancer." (PMID 37491836, 2023). "This investigation provides crucial data regarding the expression levels of GCR, SGK1, and Bcl-2 in respective breast cancer TMAs." (PMID 37370761, 2023). "We performed hierarchical clustering of ROR1 with 24 EMT-related genes including the Hippo signaling pathway genes from the MSigDB database along with WNT5a, BMI1, BCL2, and GLI1 prompted by associations noted in prior studies on breast cancer or CLL." (PMID 37029329, 2023). "Anisomycin induces apoptosis in cancers by a diversified mechanism, which can induce apoptosis in a variety of cancers, including kidney cancer, breast cancer and human glioma, by regulating the bcl-2, C-flip (L) and McL-1 pathways." (PMID 37325053, 2023). "lncRNA-SNHG14 incorporated into exosomes from trastuzumab-resistant HER-2+ breast cancer cells can disseminate resistance to sensitive cells by targeting the apoptosis regulator Bcl-2 (Bcl-2) signaling pathway." (PMID 36839784, 2023). "Cases with high Bcl-2 have a higher overall survival rate compared to cases with low Bcl-2 (log-rank p = 0.0478) and breast cancer-specific survival (log-rank p = 0.0025)." (PMID 37370761, 2023). "BCL2 is a pro-survival biomarker, and its overexpression is common in many types of human cancer including breast cancer." (PMID 38022682, 2023).
breast carcinoma (continued). "As a result, the emphasis of the current investigation is on the anticancer activity ofRauvolfia tetraphylla extracts on MCF-7 breast cancer cell lines, as well as their effects on the levels of gene expression for BCl2 and TGF." (PMID 37720282, 2023). "BCL-2 is frequently present in multiple tumors, mainly in patients with estrogen receptor-positive (ER+) breast cancer." (PMID 36766698, 2023). "Apoptosis resulted in all the treated breast cancer cell lines, as evidenced by significant decreases in BCL-2 levels and increases in BAX levels." (PMID 36770598, 2023). "There is evidence that resistin increases aggressiveness in breast cancer, favoring processes such as tumor growth by increasing BCL-2 and BCL-xL activity, accompanied by a decrease in cleaved caspase-7 and -3." (PMID 38137922, 2023). "The designed compounds demonstrated inhibitory activity against Bcl-2-expressing human cell lines, including breast cancer lines MCF-7 and MDA-MB-231 and A549 lung cancer cells at sub-micromolar concentrations, indicating their potency." (PMID 37834104, 2023). "Immunoblotting analysis showed reduced levels of antiapoptotic Bcl-2 protein in MCF-7 breast cancer cells treated with VA compared to control, while increased expression of pro-apoptotic Bax and Bad, was evidenced with the prolongation of incubation." (PMID 36864445, 2023). "Our study reported that compounds 3a and 5a induced apoptosis in breast cancer cells, as evidenced by an increased Bax/Bcl2 expression ratio and the increase in active caspase-3/7, confirming the apoptotic cascade." (PMID 37110575, 2023). "On the other hand, the exploitation of gene markers can contribute toward a better understanding of the application scenarios of BCL-2 inhibitors in breast cancer." (PMID 37894324, 2023). "BCL-2 siRNA-loaded exosome derived from NK cells was utilized to treat ER+ breast cancer cells and led to increased apoptosis in breast cancer cells." (PMID 36678782, 2023). "Similar to previous reports, the downregulation of Bcl-2, among our cases, was more evident in aggressive subtypes of breast cancer, such as ER- and/or PR- (27%), triple-negative (31%), and Her2+ (14%), compared to ER positive BC tissue." (PMID 37370761, 2023). "More large retrospective studies are warranted to rigorously investigate the role of endocrine resistance markers (ERBB2, BCL2, and CCND1) in screening FA patients with a high recurrence risk and increased risk of breast cancer." (PMID 37328469, 2023). "Nuclear localization of Bcl-2 was also observed in cells from breast cancer, endometrial carcinoma, squamous cell carcinoma, and astrocytoma." (PMID 38113109, 2023). "We detected Bcl-2 staining in 79% of breast cancer tissues compared to 100% for fibroadenoma and normal tissue." (PMID 37370761, 2023). "Bcl-2 is known to be expressed in normal and breast cancer cells and is reported to be overexpressed when the cells are treated with estrogen." (PMID 37736508, 2023). "Conversely, the expression of cytoplasmic Bcl-2 was reduced in breast cancer compared to normal tissue, especially in hormone receptor-negative cases." (PMID 37370761, 2023). "Amygdalin has been shown to induce apoptosis and inhibit the adhesion of breast cancer cells by increasing the level of pro-apoptotic Bax proteins and caspase-3 activity and decreasing the level of the anti-apoptotic Bcl-2 protein." (PMID 37762572, 2023). "In breast cancer cells, 17β-estradiol stimulates overexpression of BCL-2, which decreases levels of mitochondrial apoptotic factors." (PMID 36676192, 2023). "BH3 mimetics in combination with taxanes were efficient for breast cancer patients with paclitaxel-resistant and presented the potential effectiveness of combination targeting Bcl-2 with chemotherapy." (PMID 37237269, 2023).
breast carcinoma (continued). "Not only can they hit the universal cellular energy metabolism system by uncoupling the membranes of the mitochondria and subsequently generating ROS, but they are also potentially effective against the Bcl-2-enriched breast cancer subtype." (PMID 36557944, 2022). "Bim/Bcl-2 complexes were also found to be a prerequisite in the chemosensitization of luminal breast cancer cells to taxanes by ABT-737." (PMID 35053443, 2022). "Curcumin down regulates Bcl-2 in breast cancer cells, while up-regulating Bax, resulting in an increase in ratio of Bax/Bcl-2." (PMID 35422844, 2022). "Kae has been reported to induce apoptosis of breast cancer cell line MCF-7 intrinsically via apoptotic downregulation of Bcl2, upregulation of Bax expression, and cleavage of PARP." (PMID 36234962, 2022). "Breast cancer patients with high Bcl‐2 expression had a poor response to chemotherapy compared with those who had less Bcl‐2 expression." (PMID 35611809, 2022). "In breast cancer cells, MCF-7 and acacetin decreased Bcl-2 and released cytochrome c and AIF through the loss of mitochondrial membrane potential." (PMID 36142874, 2022). "Their results demonstrated the enhanced delivery of a nanoformulation into tumor cells and inhibition of Bcl-2 expression and Notch-1 signaling pathways in human breast cancer MDA-MB-231 cells and in nude BALB/c mice." (PMID 36153528, 2022). "STAT3 is a transcription factor for breast cancer proliferation-associated genes such as CCND1, c-myc, BCL2, and BAX." (PMID 36106139, 2022). "Univariate and multivariate analyses revealed that clinical stage and BCL2 expression were factors affecting the prognosis of breast cancer patients." (PMID 35251139, 2022). "siBCL-2 NKExos efficiently targets Bcl-2, promotes enhanced apoptosis of breast cancer cells, and has better safety for normal cells." (PMID 36290544, 2022). "Further research suggested IL-8 can inhibit the apoptosis of human breast cancer cells via up-regulating Bcl-2 and down-regulating caspase-3." (PMID 35053925, 2022). "In any case, these data indicate that endogenous Bcl-xL suppresses IP3R activity in breast cancer cells, independently of Bcl-2 levels." (PMID 34750538, 2022). "The pro-survival Bcl-2 proteins are overexpressed in ER+ breast cancer and are emerging as significant regulators of endocrine therapy resistance." (PMID 35053443, 2022). "We investigated the relationship between the risk of breast cancer and XRCC3 Thr241Met, XRCC4 G(-1394) T, BAX G(-248) A, and BCL2 C(-938) A gene polymorphisms." (PMID 35320970, 2022). "PI3K/mTOR inhibitors were shown to upregulate Bcl-2 levels in MCF-7 breast cancer cells and synergize with the BH3 mimetics ABT-737 and ABT-199." (PMID 35053443, 2022). "The anti-apoptotic protein, Bcl-2, can be regulated by p52 homodimers in conjunction with its transactivation partner, Bcl-3, in both leukemic and breast cancer cells." (PMID 35681213, 2022). "Exosomes (NKExos) encapsulated Bcl-2 siRNA (siBCL-2) transduced by lentivirus for expression and further evaluated in ER+ breast cancer." (PMID 36290544, 2022). "The Bcl-2/Bax ratio rises with the increase of PrPC levels limiting the MCF-7 breast cancer cells from going through apoptosis." (PMID 36359353, 2022). "In a prospective analysis including over 110,000 early-stage breast cancer cases, Bcl-2 upregulation was identified in 73% of breast cancers, with 86% determined in the ER+ subtype." (PMID 35053443, 2022).
breast carcinoma (continued). ",294 miR-21 has been demonstrated to cause apoptosis in human glioblastoma cells by activating caspases, whereas silencing of miR-21 decreased in vitro and in vivo growth of breast cancer cells by triggering Bcl-2 down-regulation and increasing apoptosis." (PMID 35664698, 2022). "When studding the presence of these targets we observed that BCL2 was highly expressed in lung and breast cancer and CDK4 in breast and prostate." (PMID 35249548, 2022). "Inhibition of BCL-2/BCL-XL has shown anti-cancer function in preclinical models of breast cancer where navitoclax inhibits TNBC patient derived xenograft (PDX) growth when administered in combination with docetaxel." (PMID 35349392, 2022). "We found that among all nine cell lines, breast cancer cell lines showed high expressions of BCL-2 in both assays." (PMID 36358660, 2022). "In vitro, SCA induced autophagy in breast cancer cells via the PI3K–Akt–mTOR pathway and decreased the Bcl-2/Bax ratio to induce apoptosis in breast cancer cells." (PMID 36408240, 2022). "There were no significant changes in the other biomarkers measured such as phosphate and tensin homolog (PTEN), Bax and Bcl-2.WoO studies have been widely utilised within the ER+ breast cancer subtype, demonstrating their worth in pharmacodynamic research." (PMID 36291809, 2022). "The use of BH3 mimetics in ER+ breast cancer cells was found to increase the efficacy of various therapeutic agents through targeting pro-survival Bcl-2 proteins." (PMID 35053443, 2022). "Our in vitro studies demonstrated that MY11 promoted breast cancer cell apoptosis by activating the NF-κB/PUMA/mitochondrial apoptosis pathway (including Bcl-2, Bax, and Caspase-9)." (PMID 35759135, 2022). "Flubendazole-induced apoptosis was dependent on caspase activation in breast cancer, and we also determined that flubendazole can up-regulate the pro-apoptotic protein Bax and downregulate the anti-apoptotic protein Bcl-2 in TNBC." (PMID 35440104, 2022). "Many types of cancer such as prostate cancer, myeloid leukemia, breast cancer, glioblastoma display strong chemo resistance, which is supported by enhanced expression of multiple anti-apoptotic Bcl-2, Bcl-XL and Mcl-1 proteins." (PMID 36267274, 2022). "Therefore, the acceleration of Bax, attenuation of Bcl-2, Apaf-1/cytochrome c apoptosome development, and activation of caspase-9 and -3 are supposed to explain the underlying molecular mechanisms of andrographolide that induced cell apoptosis in breast cancer cells." (PMID 35684480, 2022). "In our study, we investigated the relationship between breast cancer risk and genetic variations in DNA repair [XRCC3 Thr241Met and XRCC4 G(‐1394) T] and apoptosis [BAX G(-248) A and BCL-2 C(‐938) A] pathways." (PMID 35320970, 2022). "In PDX models of ER+ breast cancer, tamoxifen was found to increase the levels of Bcl-2 and Bim, whereas ABT-737 disrupted these complexes." (PMID 35053443, 2022). "When added to Hs578 T breast cancer cells, amygdalin (10–40 mg mL−1) drastically reduced Bcl-2 expression while increasing Bax expression and triggering the cleavage of caspase-3 and poly ADP-ribose polymerase." (PMID 36291723, 2022). "It was shown that the differentiation of breast cancer stem cells occurred by the knockdown of CD44 and caused the loss of the CSC phenotype along with the reduced expression of Bcl-2 and Muc-1 proteins, reducing metastasis and tumorigenesis." (PMID 35631686, 2022). "BCL2 raises the metabolic strength of MCF7 breast cancer cells, which was correlated with heightened mitochondrial NAD (P) H and ATP concentrations." (PMID 36299777, 2022). "Several studies have portrayed BCL-2 as a significant prognostic marker in luminal A, ER-positive subtypes of breast cancer." (PMID 36358660, 2022). "The meta-analysis strongly supports the prognostic role of BCL2 as assessed by immunohistochemistry in breast cancer." (PMID 35563727, 2022).
breast carcinoma (continued). "Curcumin significantly inhibited the growth of MDA-MB-231 and MCF-7 human breast cancer cells by inducing apoptosis in a gradual, dose-dependent method, which was related the increase in the Bax/Bcl-2 ratio." (PMID 35565294, 2022). "Several studies have indicated that bcl-2 protein expression can impaired apoptosis and is involved in the development of MDR, and MCF-7 human breast cancer cells with bcl-2 overexpression are resistant to adriamycin." (PMID 35814435, 2022). "The overexpression of Bcl-2 in breast cancer cells is involved in the cells’ proliferation and survival and has been credited with their ability to developing a resistance to therapy through the evasion of apoptosis." (PMID 36557944, 2022). "Through targeting Bcl-2, CD44, and SIRT1 (silent information regulator 1), Rac1, Fra-1, Notch-1, and different cyclins, exogenous expression of miR-34a in breast cancer cells caused cell death and decreased cell proliferation and migration." (PMID 36325275, 2022). "Actually, the BCL-2 gene involved in cell apoptosis is closely related to the occurrence of breast cancer and the proliferation of breast cancer cells." (PMID 36313628, 2022). "The B-cell CLL/lymphoma 2 (Bcl-2) family plays a major role in the process of mitochondrial-mediated apoptosis in breast cancer." (PMID 35050083, 2022). "The progression of breast cancer cells relies on the balance between proapoptotic and antiapoptotic proteins (Bax to Bcl2 genes)." (PMID 35889513, 2022). "A smaller phase 1b study measured the safety and preliminary efficacy of venetoclax in patients with ER+BCL2+ breast cancer to be similar to other the ‘modern-day’ therapies." (PMID 35788566, 2022). "The association of stigmasterol and sorafenib promoted caspase-3 activity and down-regulated levels of the anti-apoptotic protein Bcl-2 in breast cancer." (PMID 36290632, 2022). "Early and late pro-apoptotic characteristics were observed by annexin-V/7-AAD detection, accompanied by a high percentage of the Bcl-2 anti-apoptotic protein inactivated and the activation of effector Caspase-3 and/or 7 in breast cancer cells." (PMID 36615253, 2022). "PEG-FA@Nio-Cur treatment of 4T1 and MCF7 breast cancer cells reduces antiapoptotic Bcl2 expression and increases the expression level of the Bax proapoptotic gene." (PMID 35889513, 2022). "The expression of Bcl2 was affected by an oestrogen response element existing in its second exon, which is decorated by H3K27Me3 in breast cancer cells." (PMID 34999729, 2022). "BCL2 is responsible for suppression of the mitochondrial pathway activation to apoptosis, and its expression is increased in most breast cancer cases." (PMID 35164019, 2022). "A previous report indicated that Bcl-2 overexpression inhibited the induction of cell apoptosis in response to various chemical agents, including naringenin in several breast cancer cell lines." (PMID 36558554, 2022). "The Bax and Bcl-2 are up-regulated in breast cancer cell lines (MCF-7 and MDA-MB-231) by Phaseolus vulgaris (Fabaceae) extract treatment in cells, respectively (Bcl-2, Bcl-xL)." (PMID 36034846, 2022). "Studies have shown that KDM5A promotes the resistance of breast cancer cells to clinical drugs such as trastuzumab and erlotinib by blocking the regulation of p21 and BCL2-antagonist/killer 1 (Bak1)." (PMID 35493099, 2022). "In these two human breast cancer cell lines, a decrease in BCL-2 proteins was observed (black lines) but it was hard to observe the cleaved form of caspase 3 (cCaspase 3, orange lines)." (PMID 36555096, 2022).